LCN2 (lipocalin 2)
Diseases named in the same sentence as LCN2 in open-access papers (continued):
Sharing a sentence is not in itself a finding about the gene and the disease.
cancer (continued). "It is also important to fully understand the role of LCN2 in cancer progression (see Section 3) before proposing LCN2 as a truly diagnostic and/or prognostic marker for certain cancer types (i.e., aggressive cancers)." (PMID 32575507, 2020). "We also discuss the approaches to targeting LCN2 for cancer treatment that are currently under investigation, including the use of interference RNAs, antibodies, and gene editing." (PMID 32575507, 2020). "In cancer cells that exhibit LCN2 overexpression, LCN2’s modulation of MMP-9 seems to be crucial for the invasion of malignant cells through the basement membrane; this modulation occurs through three different mechanisms." (PMID 32575507, 2020). "LCN2 showed an oncogenic effect on pan-cancer, and elevated LCN2 expression was detrimental to the survival time of human cancer patients." (PMID 33425761, 2020). "In summary, the data in this study elucidated the close correlation and the prognostic significance of LCN2 expression in diverse human cancers." (PMID 33425761, 2020). "Evidence reviewed above indicates that expression of lipocalin-2 in macrophages or neutrophils can promote cancer cell growth, induce M2 polarization of macrophages and is required for neutrophil chemotaxis." (PMID 33679721, 2020). "The use of LCN2 as a prognostic marker seems to be promising; however, more studies with larger samples of cancer patients and normal controls are required." (PMID 32575507, 2020). "Several studies have demonstrated that Lcn2 expression is increased in the presence of acute or chronic inflammation, as well as in cancer." (PMID 32154171, 2020). "Neutrophil-derived lipocalin-2 induces activation of Src family kinases in prostate cancer cells and promotes cancer cell migration and metastasis." (PMID 33679721, 2020). "The results also revealed that BRCA, PRAD and THCA were three cancer types most strongly correlated with LCN2 expression in immune infiltrating level." (PMID 33425761, 2020). "Additional evidence from mouse models supports the notion that LCN2 promotes cancer cell progression and metastasis." (PMID 32575507, 2020). "Plasma and urine levels of LCN2 have been used as a biomarker for kidney disease and cancer progression." (PMID 33292361, 2020). "Several studies have reported that the aberrant expression of LCN2 can confer resistance to radiotherapy and chemotherapy in several types of cancer." (PMID 33604288, 2020). "In the last decade, the biological role of LCN2 in carcinogenesis has been addressed using mostly cancer cell lines and mouse models." (PMID 32575507, 2020). "Understanding the role of LCN2 will be essential to determining its potential as a biomarker or as a cancer therapy target." (PMID 32575507, 2020). "Increased LCN2 expression has been observed in ovarian, thyroid, breast, lung, colon, and pancreatic cancers." (PMID 32328462, 2020). "Some of these characteristics are the result of LCN2′s ability to facilitate iron intake to cancer cells or its ability to form a heterodimer with MMP-9." (PMID 32575507, 2020). "This review summarizes the most relevant findings regarding the expression, biological roles, and regulation of LCN2, as well as the proteins LCN2 interacts with in cancer." (PMID 32575507, 2020). "UPK3A, FAM3D, and LCN2, which participate cancer cell metabolisim, were also downregulated in all PDOs after CUL4B ablation." (PMID 32054830, 2020). "The LCN2 field of study would benefit from larger-sample-size studies that further evaluate the aberrant signaling pathways in LCN2-overexpressing cancer tissues." (PMID 32575507, 2020). "The discrepancy in the results demonstrates the need for further studies to clarify the various factors that potentially modulate the function of LCN2 in cancer." (PMID 32575507, 2020). "Raw data in regard to LCN2 expression in cancer patients were acquired from TCGA and GTEx databases." (PMID 33425761, 2020).
cancer (continued). "This research aimed to investigate the correlation between LCN2 expression and immunity and visualize its prognostic landscape in pan-cancer." (PMID 33425761, 2020). "In this review, we summarize the most relevant findings regarding the expression of LCN2 in neoplastic tissues of several cancers and the molecular mechanisms leading to LCN2 overexpression in cancerous cells." (PMID 32575507, 2020). "The interaction of LCN2 with MMP-9 seems to play a crucial role in the modulation of the metastatic phenotype of cancer cells." (PMID 32575507, 2020). "It has previously been shown that LCN-2 regulates neutrophil chemotaxis and cell migration in cancer cells." (PMID 31552301, 2019). "LCN2 can improve invasion abilities in CC cell lines and can activate cancer cell metastasis by increasing cancer cell motility through the activation of mesenchymal transition pathway components." (PMID 31151292, 2019). "The effect of LCN2 in cancer migration and metastasis is controversial; LCN2 overexpression in OSCC cells reduced in vitro migration and invasion and in vivo metastasis." (PMID 30871117, 2019). "Greater concentrations of LCN2 can be detected in patients with breast metastasis, which shows that it can be viewed as a cancer marker and that it relates to cell proliferation." (PMID 31151292, 2019). "Studies have shown that LCN2 plays an important role in the pathogenesis and metastasis of various types of cancer." (PMID 31151292, 2019). "LCN2 has been studied in various cancers, and it has been assigned roles in multiple cellular processes such as the suppression of the invasion of HCC cells and their metastatic abilities." (PMID 30893876, 2019). "In gastic cancer cells HGF can induce MMP-9 through upregulation in lipocalin-2 and activation of NFκB39." (PMID 30631034, 2019). "LCN2 has recently attracted the attention to its role in prognosis and diagnosis in various cancers, including colorectal and breast cancer." (PMID 30893876, 2019). "Our results point to a new paracrine activation loop between PCa cells, stromal myofibroblasts, and neutrophils involving CXCL1 and LCN2, which are shown to confer a more invasive phenotype to cancer cells by activating Src family kinases and EMT." (PMID 31500632, 2019). "Skin inflammation and some types of cancer can increase the concentration of Lcn2 in the mentioned tissues." (PMID 29755547, 2018). "LCN2 gene expression is upregulated in a diversity of cells in acute situations, including cancer, acute liver or kidney injury and infection." (PMID 30050936, 2018). "Previous studies in cancer cells have already demonstrated an inverse relationship between Lcn2 and Lcn2-R expression." (PMID 30404645, 2018). "This is in contrast to the up-regulation of LCN2 in diseases such as cancer, which is correlated with an overshooting immune tolerance and where elevated LCN2 levels are used as a clinical biomarker." (PMID 30323863, 2018). "Through literature search, we found that at least in some types of cancer, Cp, LCN2, and Postn have been reported to be upregulated." (PMID 28088789, 2017). "Lipocalin-2 is a 25 kDa glycoprotein of the lipocalin superfamily that plays a pivotal role during, for example, bacterial infections and cancer." (PMID 28804221, 2017). "Although many studies have shown that NF-κB enhances LCN2 expression to promote progression in a series of cancers, we focused on the regulation of LCN2 in NF-κB/snail pathway-induced cancer progression." (PMID 27912767, 2016). "According to previous reports, the influence of LCN2 on cell proliferating and differentiating processes can be confirmed together with its involvement in cancer development." (PMID 27602760, 2016). "So far, the role of LCN2 in cancer is still controversial and studies regarding the role of LCN2 in CCA are limited." (PMID 27782193, 2016). "Here, we provide the first evidence that LCN2 acted upstream of the NF-κB/snail pathway to prevent cancer progression." (PMID 27912767, 2016).
cancer (continued). "LCN2 belongs to a member of lipocalin family and has been shown to have pro-proliferation, pro-angiogenesis, as well as pro-metastasis effects in cancer cells." (PMID 27110769, 2016). "Although the regulatory actions of elevated LCN2 in cancer are not yet fully understood, aberrant LCN2 expression has been found under several conditions." (PMID 27912767, 2016). "These authors' investigation of the correlation between LCN2 and nm23-H1 expression in cancer metastasis suggested that the LCN2 gene is an important downstream target of nm23-H1 in SiHa cancer cells." (PMID 26840566, 2016). "Overexpression of LCN2 has also been described in several types of human cancer cells, such as colorectal, bone marrow and pancreatic cancer." (PMID 27136530, 2016). "A previous study has reported that CHOP is able to bind to the Lcn2 promoter as well and is able to induce LCN2 expression, at least, in human cancer cells." (PMID 26787103, 2016). "Lipocalin2 (LCN2) is a secretory protein that is aberrantly expressed in several types of cancer and has been involved in metastatic progression." (PMID 27912767, 2016). "Since epithelial-mesenchymal transition (EMT) is a key step in cancer cell metastasis, we then investigated the effect of LCN2 on EMT-related transcription factors." (PMID 27782193, 2016). "Our findings collectively support a potential role of T3/TR in cancer progression through regulation of LCN2 via the Met/FAK cascade." (PMID 25940797, 2015). "LCN2 (lipocalin-2), also known as neutrophil gelatinase-associated lipocalin (NGAL), is overexpressed under many other pathologic conditions, including cancer." (PMID 26131602, 2015). "Cumulative experimental results have demonstrated that LCN2 has multiple functions in various cancers, including inhibition of apoptosis, stimulation of proliferation, and promotion of the epithelial-to-mesenchymal transition (EMT)." (PMID 26131602, 2015). "LCN2 expression is dysregulated in some benign and malignant diseases, and has been shown to play multifaceted roles in cancer in a cell lineage specific manner." (PMID 24939880, 2014). "As our data demonstrated, LCN2 expression was nearly perfectly correlated with HIF-1α levels in various cancer cells derived from solid tumors." (PMID 25467539, 2014). "Increase in LCN2 expression has been reported in renal injury, inflammation, and other cancer types." (PMID 23056397, 2012). "Since LCN2 has been demonstrated to promote survival in PDAC and several cancer cell line models in vitro, we wanted to determine if LCN2 would have an effect on gemcitabine sensitivity of PDAC in vivo." (PMID 23056397, 2012). "Lcn2 plays important roles in a variety of pathological processes such as intoxication, renal injury, burn injury, human cancers and infection." (PMID 23493520, 2012). "Particularly, lipocalin-2 has gained attention as a potential biomarker and a modulator of several types of human cancers, thus a potential therapeutic target as well." (PMID 22640376, 2012). "Initially known only as an antibacterial factor of innate immunity, lipocalin-2 has been suggested to participate in diverse biological processes such as, inflammation, acute organ damage, lipid metabolism, and cancer development." (PMID 22640376, 2012). "PDAC is one of the most fatal cancers with a very poor prognosis and we have provided evidence on the importance of LCN2 in contributing to aggressive and drug resistant phenotypes." (PMID 23056397, 2012). "Our findings that LCN2 expression promotes MMP-9 activity are consistent with other cancer cell types." (PMID 23056397, 2012). "Overexpression of LCN2 has also been observed in a number of cancer types including breast, lung, ovary, thyroid, esophageal, and PDAC." (PMID 23056397, 2012). "A microarray study showed LCN2 to be the gene with largest fold change between carcinomas and benign tissues such as hyperplasia and normal endometrium." (PMID 22559235, 2012).
cancer (continued). "Validation by immunohistochemistry confirmed the increase of LCN2 expression from atypical endometrial hyperplasia to carcinomas." (PMID 22559235, 2012). "Lcn2 expression is induced in various cells under harmful conditions such as cancer, infection, and more generally inflammation." (PMID 21283804, 2011). "What signaling elements connect the UPR to NF-κB activation and Lipocalin 2 upregulation in cancer cells?" (PMID 21649922, 2011). "One expression-based study showed that levels of five proteins, including LCN2, discriminated between PaC patients and matched controls up to 13 months before cancer diagnosis." (PMID 21455317, 2011). "It was necessary to define the roles and molecular mechanisms of lipocalin 2 in given cancer metastasis." (PMID 19077278, 2008). "In addition, cancer cells used LCN2/SLC22A17 to accumulate extracellular iron in the CSF and thus outcompete other cells in the leptomeninges." (PMID 41303420, 2025). "Studies have shown that the expression level of LCN2 is increased in many malignant tumors." (PMID 39931061, 2025). "After that, LCN2 was found to accumulate in a wide range of cancers." (PMID 40109857, 2025). "Indeed, single-cell RNA-Seq demonstrated that ATG9A KO in cancer cells promoted macrophage activation towards a cytotoxic phenotype, characterized by markers such as Inos, S100a8, Lcn2, and Cox-2." (PMID 40595560, 2025). "Previous researches have shown that LCN2 acts in distinct roles in regulating ferroptosis of distinct cancers, and its role in GC ferroptosis remains unclear." (PMID 40109379, 2025). "Thus, LCN2 serves as a key link between innate immune activation and cancer progression, highlighting how innate immune components can be reprogrammed by tumors to favor their own survival and spread." (PMID 41303420, 2025). "The specific actions of LCN2 in tumors may vary depending on the particular type of cancer involved." (PMID 40109857, 2025). "Recent studies have shown that LCN2 increased cancer cell stemness through increased iron uptake." (PMID 41303420, 2025). "Since dysregulated iron homeostasis and a high demand for iron is an unofficial hallmark of cancer, it is plausible to hypothesize that JIMT-1-induced LCN2 upregulation in macrophages may contribute to TAM polarization." (PMID 38612413, 2024). "Notably, recent studies have shown that LCN2 is abnormally expressed in a variety of cancers, including breast, colon, pancreas cancers." (PMID 39424639, 2024). "Importantly, LCN2 has been found to be abnormally expressed in a range of cancers, such as breast, colon, and pancreatic, with recent studies highlighting its significant association with cancer initiation and progression." (PMID 39850877, 2024). "Moreover, LCN2 is also known to associate with MMP9, preventing the degradation of the metalloproteinase that is involved in degrading ECM, enhancing cancer metastasis." (PMID 38612413, 2024). "Furthermore, the initial signals that have been reported to promote formation of the premetastatic niche include cancer‐derived mediators, most notably the S100 family genes and LCN2,69, 70, 71 which is also consistent with our findings." (PMID 39003681, 2024). "Given the prevalent local hypoxia in most solid tumours, LCN2 may play pivotal roles in hypoxic glycolysis in cancer cells as well." (PMID 39021353, 2024). "There are several mechanisms involved in the regulation of a variety of cancers by LCN2." (PMID 38673873, 2024). "LCN2 is overexpressed in various cancers and has been identified as a potential therapeutic target." (PMID 39424639, 2024). "LCN2 may serve as a genetic biomarker for immune infiltration and poor prognosis in cancers, suggesting potential therapeutic targets for cancer treatment." (PMID 38609844, 2024). "Expression levels of LCN2 in cancers of the human female reproductive tract." (PMID 38645429, 2024). "LCN2‐activated Akt signalling has also been observed in cancer cells." (PMID 39021353, 2024).
cancer (continued). "Elevated expression levels of LCN2 have been found in aggressive subtypes of cancer." (PMID 36926025, 2023). "Next, we performed a mammary sphere formation assay to examine whether neutrophils promote cancer stemness by LCN2." (PMID 37174093, 2023). "Probably, the combination therapy or personalised treatments targeting at FATP2 and lipocalin-2, together with metformin, might be the solutions to attenuate steatotic graft injury and subsequently reduce cancer recurrence after transplantation." (PMID 37916155, 2023). "Nevertheless, it seems that targeting Lcn-2, alone or combined with other targets, could be considered a good option to induce the ferroptosis of cancer cells." (PMID 37958332, 2023). "Therefore, Lcn-2, a transferrin-independent iron carrier, allows cancer cells to acquire the additional necessary iron." (PMID 37958332, 2023). "Indeed, LCN2 involvement in different types of cancers has led pharmacological research to focus on different mechanisms to inhibit LCN2, both at the gene and protein level." (PMID 36671482, 2023). "Recently, LCN2 was identified as a promotor of cancer progression." (PMID 37684641, 2023). "We identified LCN2 as a potential target in the treatment of cancer cachexia." (PMID 36973755, 2023). "Therefore, we concluded that the LCN2/LOXL2/MMP9 ternary complex promoted the invasion of cancer cells by degrading laminin and type IV collagen." (PMID 37753805, 2023). "Moreover, it is supported that cancer cells employ Lcn2 to collect extracellular iron to support cancer growth in renal cell carcinoma and leptomeningeal metastasis." (PMID 35785195, 2022). "Interestingly, the expression pattern and functional role of LCN2 appear to vary depending on the type of cancer." (PMID 35470375, 2022). "Using computational and immunohistochemistry examinations, LCN2 expression has been shown to be a suppressor of invasion and angiogenesis in six cancer types, such as bladder, colorectal, liver, lung, ovarian and pancreatic when compared to matched primary lesions." (PMID 36428800, 2022). "Given the conflicting observations, LCN2 might play a dual role according to cell type, cancer type and organ type." (PMID 35705840, 2022). "High level of LCN2 was correlated with low survival in all cancer patients." (PMID 36428623, 2022). "LCN2 has been found as a biomarker for several diseases and cancers." (PMID 36428800, 2022). "Therefore, further experiments are required to directly address this issue to ensure a better understanding of the interaction of LCN2 with SAA1 in cancer and to figure out the role of SAA1 in GC cells in the future." (PMID 35705840, 2022). "This seems to be a promising proposition, as siderophore-iron complexes can bind Lcn2 and travel in circulation, and iron-loaded Lcn2 can be taken up by cancer cells where Lcn2 is commonly upregulated, creating a pathway for the implementation of a modified “Trojan horse” drug delivery." (PMID 35785195, 2022). "LCN2 can either promote or suppress tumorigenesis in different cancer types." (PMID 35053376, 2022). "In both primary hepatocytes and cancer cell lines, IL-1β is known as a potent inducer of LCN2." (PMID 35053376, 2022). "However, the remarkable overlap in the behavioral and transcriptomic response to cancer and to LCN2 administration serves to strengthen the connection between hypothalamic responses and systemic inflammation." (PMID 35031523, 2022). "LCN2 is primarily an iron-trafficking protein involved in the regulation of cellular iron ion homeostasis, and recent studies have shown that LCN2 had multiple functions involved in various biological and pathological processes including energy homeostasis, cancer, inflammation, and apoptosis." (PMID 34903175, 2021). "LCN2 is also a potential therapeutic target in cancer and other diseases." (PMID 34342930, 2021).